INS (insulin)
Diseases named in the same sentence as INS in open-access papers (continued):
Sharing a sentence is not in itself a finding about the gene and the disease.
Autoimmunity (continued). "The outcomes of this study demonstrated that pre- and posttransplant autoimmunity were associated with delayed insulin non-requirement and autoimmunity was directly proportional to the recipients’ circulating C-peptide 1 year post-transplant." (PMID 28066448, 2016). "Importantly, the majority of early insulin autoimmunity children had anti-VP2 or anti-VP4 antibodies at age 3 years, suggesting that they had been previously exposed to CVB." (PMID 27604323, 2016). "We asked whether the low anti-VP1 antibody response observed in the children with early insulin autoimmunity could reflect a defective maternal CVB antibody status at birth." (PMID 27604323, 2016). "Irrespective of the presence or duration of autoimmunity all insulin-variants were superior in stimulating insulin-specific CD4+T-cell clones." (PMID 26975663, 2016). "Such a therapy could be tested initially in newly diagnosed patients, many of whom retain sufficient insulin production to prevent diabetic complications, and, if successful, lead to the treatment of autoimmunity to prevent the metabolic diagnosis of T1D." (PMID 27727279, 2016). "Against this background, we hypothesized that alcohol may prevent or delay the onset of LADA, either through beneficial effects of alcohol on insulin sensitivity or through effects on autoimmunity." (PMID 25117461, 2014). "Understanding how recognition of insulin could endow pathogenic and/or regulatory roles to CD4+ T cells will help us understand how organ-specific autoimmunity develops and how it can be controlled." (PMID 25393309, 2014). "As revealed by the studies on anti-insulin autoimmunity, the stimulation provided by antigenic peptide-MHC stimulation could also be modulated by genetic variations of the insulin gene, influencing the gene expression in the thymus." (PMID 22007255, 2012). "Although leptin resistance presented early in BWF1 mice can slow-down the progression of autoimmunity, our results suggest that sustained insulin stimulation of organs, such as liver and probably kidneys, facilitates the over-expression and activity of mTOR and the development of SLE." (PMID 23226562, 2012). "It is possible that the intervention may be more effective in these individuals due to a more active autoimmunity against insulin." (PMID 21647401, 2011). "INS-VNTR class-I has also been shown to be associated with lower expression of Insulin in thymii of fetuses as compared to Class-III alleles which may be responsible for poor thymic education for insulin resulting in autoimmunity against pancreatic beta cells." (PMID 19956544, 2009). "Therefore, both key issues (autoimmunity and shortage of insulin-producing cells) for recent onset of T1D have been overcome simultaneously by the treatment with mCD4CD62L Tregs." (PMID 19156219, 2009). "The effects of insulin autoimmunity on the pancreas are only poorly known." (PMID 15543375, 2004). "Therefore, inducing insulin-specific Tregs holds promise for effectively controlling autoimmunity." (PMID 41567805, 2025). "Interestingly, reduced insulin sensitivity in CD4+ cells may protect against the immunosuppressive effects of insulin, preserving effector T cell activity and enhancing autoimmunity." (PMID 39768214, 2024). "Thus, our findings that in vitro T cell responses to insulin were more likely to occur in CD169+ samples in children with the susceptible INS AA genotype may be relevant to the mechanism of insulin autoimmunity." (PMID 33515070, 2021). "Developmental exposure to EDCs can have effects that could be important in the development of T1DM, including promoting autoimmunity, affecting the development of the pancreas and beta cells specifically, influencing insulin secretion, and disrupting metabolism." (PMID 30233498, 2018). "We have shown that autoimmunity to insulin may result from neoepitopes induced by oxPTM." (PMID 28526919, 2017).
Autoimmunity (continued). "The present study shows that E2, used at physiological concentrations, improves islet engraftment in a sex-non-specific manner in an insulin-deficient nude mouse model transplanted with a marginal dose of human islets and in the absence of allorejection or autoimmunity recurrence." (PMID 23132340, 2013). "Finally, one could construct a model that includes more detail regarding the different timescales for insulin production, insulin signaling, and beta cell autoimmunity." (PMID 22973412, 2012). "Similarly to insulin gene polymorphisms affecting central tolerance through the level of gene expression in thymus, we were looking for an association between the two FSHB core haplotypes and autoimmunity against FSH." (PMID 22007255, 2012). "An alternative hypothesis is that dietary cow's milk insulin could trigger beta-cell autoimmunity." (PMID 22567309, 2012). "This is probably due to a combination of factors, which include a physiological age-related decline in β-cell mass, differences in insulin needs according to body weight, growth and insulin sensitivity, and the degree of β-cell autoimmunity, which may be more aggressive in younger patients." (PMID 21647401, 2011). "Conversely, the unaltered diabetogenic effect of IDE deficiency in mice reconstituted with 8.3 bone marrow confirmed the selective impact of this enzyme on insulin-specific CD8+ T cell responses, leading to reduced autoimmunity in Ide-/- mice." (PMID 39600694, 2024). "Studies using T cells specific for the INS B chain, which is often considered to be the main target of T1DM autoimmunity, have identified Streptococci, Clostridia, Escherichia coli, and Pseudomonas as potential mimics." (PMID 37176044, 2023). "Supporting the notion that the inflammatory milieu fosters autoimmunity, CD4+ T cells are more likely to exhibit proinflammatory responses to insulin in vitro when the antigen is presented by CD169-expressing monocytes." (PMID 37231274, 2023). "We and others have shown that autoimmunity to insulin often precedes autoimmunity to GAD, and the TEDDY study defined insulin-first and GAD-first endotypes." (PMID 31286933, 2019). "In previous studies we showed that hAAT reduced anti-insulin auto-antibodies (IAA) and attenuated cell-mediated autoimmunity." (PMID 21345239, 2011). "However, it is not clear whether it is associated with autoimmunity in addition to insulin secretion and resistance." (PMID 19471607, 2008). "This interaction suggests that insulin-mediated mTORC1 activation may also augment IFN-I production in pDCs, aggravating autoimmunity or boosting anti-viral responses." (PMID 36992811, 2023). "In fact, one study shows that successful withdrawal of insulin treatment was possible in 22.6% of patients with T1D and negative autoimmunity." (PMID 37138364, 2023). "The clinical diagnoses of T2D were confirmed as all included participants had remaining insulin secretion without immunological signs of autoimmunity." (PMID 36348470, 2022). "It is well known that islet grafts are attacked by T1DM autoimmunity in NOD mice, but it is unknown as to what happens to syngeneic-transplanted insulin-producing cells." (PMID 35393479, 2022). "Islet autoimmunity was assessed as T cell proliferation upon stimulation with the beta cell antigens GAD65, islet antigen-2 (IA-2), preproinsulin (PPI) and defective ribosomal product of the insulin gene (INS-DRIP)." (PMID 31754749, 2020). "The phenotypic and functional effects of betamethasone was accompanied by changes in the expression of genes related to autoimmunity, metabolism and islet mass, both in NIT-1 cells and islets such as a downregulation of Igf1r and a hyperexpression of Ptprj –both genes related to insulin sensing." (PMID 30718757, 2019). "Higher insulin, C-peptide, HOMA-IR, low-density lipoprotein/HDL, systolic blood pressure and lower HDL levels in vitiligo were reported in their study due to increased cytokines and autoimmunity to melanocytes." (PMID 28443562, 2017).
Autoimmunity (continued). "Heterogeneity in the development of beta cell autoimmunity was defined by target autoimmunity (insulin, GAD, or none) age (before or after age 3 years) defined in children who were prospectively followed to beta cell autoimmunity from birth." (PMID 27604323, 2016). "Demonstrating the broad range of applications of this vaccine strategy for suppression of autoimmunity, conjugation of CTB with islet auto-antigens such as insulin and glutamic acid decarboxylase (GAD) was shown to induce immunological tolerance through the suppression of DC maturation." (PMID 25714914, 2015). "Moreover, the HT group had similar anthropometric parameters, lipid profile, glucose, and insulin concentrations compared to controls without autoimmunity." (PMID 38892627, 2024). "We are also unable to assess insulin autoimmunity in our cohort as all participants were insulin treated, meaning we would be unable to distinguish between insulin autoantibodies (IAA) recognising exogenous insulin (immunity) and IAA to endogenous insulin (autoimmunity)." (PMID 35501400, 2022). "The EVs signals from insulin-producing beta-cells affected by autoimmunity might not be successfully assessed in a cohort of nT1D individuals, because of variably in the preserved beta-cells mass." (PMID 32296701, 2020). "However, our experiments also show that while the congenital substitution of the B:9-23 insulin epitope alone is sufficient to prevent autoimmunity, it is not sufficient to fully suppress assault in NOD animals congenitally sensitized to insulin." (PMID 30899071, 2019). "In T1D, autoantibodies to islet antigens–insulin (IAA), glutamic acid decarboxylase 65 (GAD), islet cell cytoplasmic antigens (ICA), zinc transporter 8 (ZnT8), and protein tyrosine phosphatase-like protein (IA-2/ICA512) are validated biomarkers of autoimmunity." (PMID 31795194, 2019). "In our study, patients’ insulin free for longer periods presented higher C-peptide levels, higher Treg numbers, and lower autoreactive CTL frequencies, suggesting that Tregs might have played a role in controlling autoimmunity." (PMID 28275376, 2017). "All children who developed early insulin autoimmunity had no or weak anti-VP1 antibody responses." (PMID 27604323, 2016). "Current investigations in humans at risk for T1D still do not answer the question what factor may trigger the insulin autoimmunity." (PMID 22567309, 2012). "Several hypotheses try to explain these findings, including lack of insulin as a trophic factor for exocrine tissue, changes in secretion and/or action of other islet hormones, and autoimmunity against common endocrine and exocrine antigens." (PMID 21822421, 2011). "Given the importance of INS autoantibodies, as well as anti-GAD and anti-PTPN(IA-2) autoantibodies and TCR, in T1DM, and the failure of COX antibodies to recognize these antigens, a critical question is whether there needs to be a second microbe that triggers concomitant anti-INS autoimmunity." (PMID 37176044, 2023). "In response to ER stress, for example, insulin and GAD65 proteins undergo inappropriate post-translational modification and/or folding and the modified protein products are believed to act as immunogenic neoautoantigens that could be presented by the MHC to induce β-cell autoimmunity." (PMID 33584694, 2020). "However, our findings of robust anti-VP1 antibodies in cord blood of the newborns who developed either insulin or GAD targeted autoimmunity did not support this hypothesis." (PMID 27604323, 2016). "Of interest, frequencies of insulin mimetope-specific Foxp3+Tregs were significantly lower in children with recent onset of autoimmunity than in children without autoimmunity (no autoimmunity versus recent onset of autoimmunity: 1.9±0.9 versus 0.5±0.4% of Tet+CD4+T cells, P<0.05)." (PMID 26975663, 2016).
Autoimmunity (continued). "Based on our findings, we hypothesize that alcohol intake through beneficial effects on insulin sensitivity may prevent or delay onset of LADA in the presence of mild autoimmunity, but that an insulin-sensitizing effect may not counter the impact of a more pronounced autoimmune process." (PMID 25117461, 2014). "Additionally, Mamchak and colleagues proved that anti-CD3 monoclonal antibody treatment with oral insulin intake improved the blood glucose level of diabetic NOD mice by increasing regulatory T cells and decreasing CD4 + CD25+ T cells, indicating a suppression of autoimmunity." (PMID 23346100, 2012). "Third, IA-2 and GAD antibodies are more likely to appear after anti-insulin antibodies and correlate with an older age of T1D diagnosis, suggesting that their appearance may occur during epitope spreading and disease progression rather than the primary insult that triggers autoimmunity to β-cells." (PMID 39211046, 2024). "Therefore, when ketosis is present at diagnosis, in the absence of autoimmunity and the presence of beta-cell function, patients may be able to discontinue insulin and maintain glycemic control using appropriate diet, exercise, and oral hypoglycemic agents in follow-up." (PMID 33905625, 2021). "While we have not addressed whether anti-insulin B cells are specifically recruited via a chemokine receptor, it is conceivable that anti-insulin B cells express high levels of C-X-C motif chemokine receptor 3 (CXCR3), a chemokine receptor involved in recruitment of lymphocytes in autoimmunity." (PMID 31444529, 2019).
hepatoma (238 papers, 2001 to 2026). "IGFALS, crucial for the stability of circulating insulin growth factors, is down-regulated in hepatocellular carcinoma and associated with poor prognosis." (PMID 41155404, 2025). "Excessive insulin levels were found to be significantly associated with an increased risk of hepatocellular carcinoma." (PMID 39530097, 2024). "Insulin encourages tumor growth in vitro; in clinical series, the need for exogenous insulin therapy was associated with an increased risk of recurrence of colorectal cancer and hepatocellular carcinoma." (PMID 29723245, 2018). "A methylation deficit should then decrease the methylation of PP2A and boost the mitotic insulin signals for choline deficiency, steatosis and hepatoma." (PMID 21649891, 2011). "A recent retrospective study involving a large sample size of 1,890,020 diabetic patients found that GLP-1RAs were associated with a significantly lower risk of hepatocellular carcinoma compared to insulin and other diabetic medications over a 5-year follow-up period." (PMID 39318780, 2024). "For instance, treatment of H35 rat hepatoma cells with the broad-spectrum zinc chelator, 1,10-phenathroline, reduced insulin degradation and led to increased accumulation of (125I)-insulin in the nucleus, together with increased association of (125I)-insulin specifically with cytosolic IDE." (PMID 33668109, 2021). "However, there are some retrospective data associating insulin treatment with fibrosis and hepatocellular carcinoma and these are discussed in more detail below." (PMID 26856933, 2016). "In addition, insulin treatment has retrospectively been associated with hepatocellular cancer." (PMID 33596938, 2021). "Additionally, studies have shown that insulin directly promotes fat accumulation in liver cells, further contributing to nonalcoholic steatohepatitis, which is an increasingly frequent cause of cirrhosis, hepatocellular carcinoma, and liver failure." (PMID 24397589, 2014). "HepG2 is a human hepatoma cell line with hepatic properties such as lipid metabolism, glycogen synthesis, and insulin signaling." (PMID 40351361, 2025). "An in vitro study was conducted to investigate the cellular uptake and compartmentalization of internalized insulin in human hepatocellular carcinoma-derived HepG2 cells using confocal laser scanning microscopy." (PMID 41200400, 2025). "This study investigates the cellular uptake and intracellular fate of fluorophore-labeled human insulin in hepatocellular carcinoma-derived HepG2 cells using confocal microscopy." (PMID 41200400, 2025). "In vitro, human hepatocellular carcinomas (HepG2) cell was used as experimental cell line, and an insulin resistant HepG2 cell model (IR-HepG2) was constructed using free fatty acid induction." (PMID 39421985, 2024). "The aim of this study was to evaluate the role of phosphoeleganin (PE), a polyketide purified from the Mediterranean ascidian Sidnyum elegans, and its derivatives PE/2 and PE/3 on insulin sensitivity in human hepatocellular carcinoma (HepG2) cells." (PMID 38892230, 2024). "First, we show an example of visualizing a trans-omic network for acute insulin action in rat hepatoma Fao cells." (PMID 38374087, 2024). "Several studies have used hepatoma cell lines, especially HepG2 cells, to study hepatocytes in insulin signaling or metabolism." (PMID 39458809, 2024). "Based on proteomic analysis, HepG2 insulin-resistant hepatoma cells grown on C60 nanofilm had altered levels of proteins involved in the transport of glucose transporter type 4 (GLUT4) to the plasma membrane of hepatocytes." (PMID 38067256, 2023). "In this study, in vitro and in vivo experiments were conducted to identify the altered biological behaviour of insulin-resistant hepatoma cells (HepG2/IR), and we proved that HepG2/IR cells had stronger malignant biological behaviour." (PMID 37328795, 2023).